CRP (C-reactive protein)
Diseases named in the same sentence as CRP in open-access papers (continued):
Sharing a sentence is not in itself a finding about the gene and the disease.
COVID-19 (continued). "The significant increase of inflammatory biomarkers, such as serum amyloid A, IL-6, and CRP in severe COVID-19 patients, are directly or indirectly linked to adipocytes with sub-clinical low-grade inflammation that further exacerbates COVID-19 severity in individuals with obesity." (PMID 34220807, 2021). "Elevated CRP levels and hypoproteinemia are not only the key indicators of disease severity but also the risk factors for death in patients with severe COVID-19 and are indicative of a cytokine storm, a common occurrence in patients with COVID-19." (PMID 34900028, 2021). "The results of the CPH model showed that comorbidities, hypertension, lymphocyte counts, platelet count, and C-reactive protein level, may increase the risk of death due to the COVID-19 as risk factors in inpatients cases." (PMID 34289910, 2021). "However, multivariate logistic regression analysis showed that among these combined biomarkers, only the CRP/Alb ratio was an independent risk factor for disease progression in patients with severe COVID-19." (PMID 34900028, 2021). "In conclusion, these cases suggest that S-MSCs could effectively control D-dimer, CRP level and GGOs of severe COVID-19 patients associated with recovered pulmonary function." (PMID 35350705, 2021). "Multivariable regression analysis showed that the Shannon diversity index [odds ratio (OR) = 2.85, 95% CI = 1.09–7.41, p = 0.032) and C-reactive protein (OR = 3.45, 95% CI = 1.33–8.91, p = 0.011) are risk factors for severe COVID-19 (a score of 6 or higher in the WHO Clinical Progression Scale)." (PMID 34349747, 2021). "Indeed, higher levels of inflammatory markers including C-reactive protein (CRP), neutrophil-to-lymphocyte ratio as well as various inflammatory cytokines and chemokines were found to be linked to more severe clinical course in COVID-19 patients." (PMID 34855832, 2021). "Laboratory findings associated with severe COVID-19 are decreased albumin, high C reactive protein, high lactate dehydrogenase, lymphopenia, eosinopenia, high erythrocyte sedimentation rate, leucopenia or leucocytosis, hyperbilirubinemia, elevated liver enzymes and high creatinine." (PMID 32788312, 2021). "CRP can be used as diagnostic parameter, and also reflect the severity and prognosis of COVID-19." (PMID 34447386, 2021). "C-reactive protein, a protein whose expression is driven by IL-6, is a biomarker of severe infection that has been associated with the inflammation cytokine storm related to COVID-19." (PMID 33657157, 2021). "The objective of this cohort study was to determine whether elevated CRP in early COVID-19 was associated with 14-day mortality in geriatric patients." (PMID 34506514, 2021). "Likewise, a blood CRP concentration ≥ 96.8 mg/L is associated with a score of 6 or more in the COVID-19 WHO Clinical Progression Scale, in accordance with our multivariate model." (PMID 34349747, 2021). "Taken together, CRP might play a vital role in the process of inflammatory response, and it can be used to assess the severity of COVID-19 and be independently associated with the risk of COVID-19." (PMID 34447386, 2021). "Similar to this situation, the high ratio of ferritin/CRP was closely associated with clinical deterioration in COVID-19, for which our experience suggested the requirement of the combination treatment of corticosteroids and tocilizumab, although further studies are essential to confirm this." (PMID 34631752, 2021). "By applying our CRP-based method to align the progression of neutrophils and lymphocytes, we were able to define a pathophysiological window that improved mortality risk stratification in our COVID-19 patient cohort." (PMID 34307391, 2021). "Future studies will need to focus on the relation between clinical measures of pulmonary function (e.g., P/F), inflammatory response (e.g., CRP), viral load, and hypercoagulability (e.g., D-dimer) and the risk of developing cognitive deficits following hospitalization for COVID-19." (PMID 33668456, 2021).
COVID-19 (continued). "In addition, leukocytosis, elevated C reactive protein levels and D-dimer, which were commonly seen in COVID-19 patients, were identified as risk factors of ICH among patients without COVID-19 infection." (PMID 32765952, 2020). "The second phenotype presents TTH characteristics (particularly pressing quality, not aggravated by movement and mild or moderate pain intensity) and is linked to lower PCT and CRP levels, both potential biomarkers of COVID-19 severity when high levels are present." (PMID 33391152, 2020). "Furthermore, the authors showed that besides those patients with severe COVID-19, older patients and those with higher vascular risk profile or C-reactive protein or D-dimer levels were at significantly higher risk of stroke." (PMID 33046957, 2020). "The NRI adjusted for CRP was also associated with severe COVID-19 (p < 0.01)." (PMID 33260603, 2020). "As determined by the multivariate analysis, CRP (OR 1.026, P = 0.018) and lymphocyte proportion (OR 0.924, P = 0.009) were significantly associated with the risk of developing severe events in fevered adult COVID-19 patients." (PMID 32719804, 2020). "Higher serum CRP can also be used to predict the risk of death in patients with severe COVID-19." (PMID 32746957, 2020). "An increase in the CRP level, as well as the extent of the increase, may be associated with the severity of COVID-19." (PMID 33275609, 2020). "Age over 12 years and initial CRP were associated with need for PICU admission in COVID-19." (PMID 33340348, 2020). "Moreover, studies have reported that pro-inflammatory factors such as CRP, interleukin 6, neutrophils, etc. were associated with the severity and prognosis of patients with COVID-19." (PMID 33192519, 2020). "Another explanation for age-associated severity of COVID-19 may be attributed to C-reactive protein (CRP)." (PMID 32321823, 2020). "Concerning the inflammatory markers associated with the COVID-19 pandemic, this comprehensive meta-analysis study observed higher concentrations of C-reactive protein (CRP) and procalcitonin besides elevated erythrocyte sedimentation rate (ESR) levels among severe and expired patients with COVID-19." (PMID 32822430, 2020). "We believe that CRP is an ubiquitously measured biomarker whose result could potentially help clinicians assess the risk of MV in patients with COVID-19." (PMID 33186355, 2020). "The results of previous observational studies suggest that lymphopenia, ferritin, D-Dimer, and C-reactive protein (CRP) might be associated to a worse evolution of COVID-19 patients." (PMID 33182268, 2020). "Our findings suggest that diabetic patients have an increased risk of in-hospital mortality following COVID-19; also, lymphocyte count, creatinine and CRP concentrations could be considered as significant predictors for the death of COVID-19 in these patients." (PMID 32641974, 2020). "Being of Asian ethnicity [3.73 (1.28–10.91)], receiving palliative treatment [5.74 (1.15–28.79)], having an initial cancer diagnosis >24 months before [2.14 (1.04–4.44)], dyspnea [4.94 (1.99–12.25)], and increased CRP levels [10.35 (1.05–52.21)] were positively associated with COVID-19 death." (PMID 32903324, 2020). "Albumin adjusted for CRP level was still associated with severe COVID-19 (p = 0.03)." (PMID 33260603, 2020). "This study aimed to determine whether patients with elevated CRP, TNFα, and IL-6 levels may be at increased risk for severe infection and liver damage of COVID-19." (PMID 33244370, 2020). "However, our observations of a positive association with CRP levels is in line with most COVID-19 studies published to date." (PMID 32903324, 2020). "Similarly, we noted that dyspnea at presentation, high CRP levels, and low levels of albumin were associated with death from COVID-19." (PMID 32903324, 2020).
COVID-19 (continued). "Defining the trends and prognostically-relevant thresholds of CRP in critically ill adults with COVID-19 may facilitate risk stratification, and guide clinical management, and help predict resource utilization." (PMID 33216774, 2020). "As the first line of innate host defenses for clearance of viral infections, CRP might be linked to the overproduction of inflammatory cytokines in severe patients and may lead to dysfunction of various organ systems in COVID-19-infected patients." (PMID 33244379, 2020). "Conversely, APTT prolongation may be related to the transient increased levels of antiphospholipid antibodies, a situation encountered during viral infections, including COVID-19, or when CRP is high, thus leading to a risk of heparin underdosage." (PMID 32922211, 2020). "At the initial stage of COVID-19, the level of inflammation and lung lesions were positively linked with CRP levels, and thus, CRP levels could signify disease severity and were suggested to be utilized as a major marker for disease monitoring." (PMID 33239068, 2020). "We performed Cox regression analysis, which demonstrated that comorbidity (HR 3.17, 95% CI 1.96–5.11), ALB level (HR 3.67, 95% CI 1.91–7.02), CRP level (HR 3.16, 95% CI 1.68–5.96), and age ≥60 years (HR 2.31, 95% CI 1.43–3.73) were independent risk factors for severe COVID-19 in these patients." (PMID 33330318, 2020). "In our study, we found an association between IL-6 and CRP in critically COVID-19 patients; this finding was already reported in other studies and is related to the effects of IL-6 and other cytokines on hepatic synthesis of inflammatory proteins, such as CRP." (PMID 33382773, 2020). "Hence, comorbidity, ALB, CRP, and age ≥60 years were identified as the most influential risk factors for the severity of COVID-19 in these patients." (PMID 33330318, 2020). "Four factors identified to be significantly relevant to the severity of COVID-19 were underlying diseases (X1), fast respiratory rate (>24 times/min) (X2), elevated C-reactive protein level (CRP > 10 mg/L) (X3), and elevated lactate dehydrogenase level (LDH > 250 U/L) (X4)." (PMID 33123541, 2020). "Our study indicates that age, the absolute lymphocyte count at initial visit, and CRP may be used as predictors during the early stage of diagnosis in patients who are at risk of developing severe COVID-19." (PMID 32589691, 2020). "- Comorbidity, ALB, CRP, and age ≥60 years are independent risk factors for severe COVID-19." (PMID 33330318, 2020). "The tight correlations we observed between CRP, ferritin, IL-6, and fibrinogen, together with their steep gradients across outcome groups, are consistent with a hyperferritinemic, macrophage-activation-like phenotype that has been repeatedly implicated in critical COVID-19." (PMID 41463074, 2025). "Moreover, the CRP levels were found to be significant risk factors for COVID-19 severity in pregnant women that might have association with comorbidities." (PMID 38905361, 2024). "Paying attention to the indicators of CRP, D-dimer, and CK-MB in patients and providing relevant symptomatic treatment as early as possible can improve patient prognosis and reduce the risk of death among COVID-19 patients with underlying cardiovascular diseases." (PMID 38835792, 2024). "Among the laboratory markers, elevated levels of ferritin, C-reactive protein, D-dimer, troponins, and lactate dehydrogenase, alongside reduced levels of monocytes, lymphocytes, and platelets, have been identified as factors associated with a higher risk of complications and death from COVID-19." (PMID 38601541, 2024). "Furthermore, COVID-19-induced systemic inflammation has been proposed to potentially cause myocardial injury in COVID-19 patients which is initially presented with abnormal C-reactive protein (CRP), N-terminal fragment of pro-BNP (NT-proBNP), and creatinine levels." (PMID 39395941, 2024).
COVID-19 (continued). "Indeed, prior small-scale clinical studies in hospitalized infected patients have assessed the accuracy of using elevated levels of biomarkers such as the inflammatory coagulation biomarkers—D-dimer and C-reactive protein (CRP)—in predicting COVID-19 prognosis and mortality risk." (PMID 39402606, 2024). "Interestingly, the diagnostic protocols for patients with severe COVID-19 (e.g., measuring inflammatory markers such as CRP and procalcitonin [PCT]) may, in some cases, have contributed to faster TC detection, particularly for medullary thyroid cancer (MTC)." (PMID 39767735, 2024). "Moreover, in logistic regression analysis, baseline CRP values above 0.8 mg/dl in COVID-19 patients were associated with a 9-fold risk for compromised endothelial function (i.e., LnRHI values below 0.51) during the acute phase (OR: 9.0; 95% CI: 1.47–81.4, p = 0.027)." (PMID 39598310, 2024). "Endocan is a modern biomarker and could emerge as an innovative parameter to evaluate the associated risks in COVID-19 patients; nevertheless, more studies are needed to assess the relationship with inflammatory and thrombosis markers (CRP, fibrinogen, D dimers, IL 6) or CT scans." (PMID 38474287, 2024). "Therefore, our objectives were to explore the association between chronic, acute, and acute-on-chronic hyperglycaemia and CRP levels during hospitalisation and the association between CRP levels at admission and insulin resistance in patients with non-COVID-19 CAP." (PMID 38202252, 2023). "However, in the present study, the multivariate logistic regression showed that ANA positivity was an independent protective factor for the disease severity of COVID-19, while age, WBC, and CRP were independent risk factors for the disease severity of COVID-19." (PMID 38107861, 2023). "Additionally, the cytokine storm seen in COVID-19 could be damaging, and interestingly, we found a significant association between the peak level of CRP and the mid-term presence of reticular changes and decreased DLCO." (PMID 36769648, 2023). "Not only can CRP levels predict COVID-19-associated severe pneumonia early, but they were also shown to be elevated in patients with a poor COVID-19 prognosis, in patients who dies from COVID-19-related causes, and in patients with additional COVID-19-related radiological lesions and tissue damage." (PMID 37789255, 2023). "Secondly, CRP, severe course of disease (each p < 0.001), and obesity (p < 0.05) were significantly and independently associated with the percentage of pulmonary infiltrates in COVID-19, opposite to age, chronic pulmonary disease, and chronic kidney disease (each p = n.s)." (PMID 37733154, 2023). "However, whether elevated CRP levels are responsible for the association between older age and higher risk of severe COVID-19 needs clarification." (PMID 38003780, 2023). "While certain Actinomyces taxa were associated with mild or moderate forms of COVID-19, a decrease in their abundance was observed in severely affected individuals, and they were also negatively correlated with inflammatory biomarkers such as C-reactive protein." (PMID 38004715, 2023). "Inflammation due to COVID-19 could potentially trigger the immune system causing liver damage, as higher levels of the C reactive protein (CRP), serum ferritin, LDH (lactate dehydrogenase), D-dimer, IL-2, and IL-6 are found in patients with severe COVID-19 infection." (PMID 37958904, 2023). "This may be related to the fact that CRP is an indicator of cardiovascular risk, inflammation and endothelial dysfunction, and vascular and renal injury, in addition to the fact that it is found to be rapidly increased after a positive diagnosis of COVID-19." (PMID 37765098, 2023). "In addition, a retrospective study of 163 COVID-19 patients greater than 18 years of age showed that all-cause mortality was associated with lower levels of lymphocytes and NK cells, and higher levels of leukocytes, neutrophils, and high sensitivity CRP." (PMID 37928548, 2023).
COVID-19 (continued). "Interestingly, in a cohort study conducted on 2782 COVID-19 subjects, the serum CRP levels above 108 mg/L were associated with a 32.2% mortality rate (compared to only 17.8%, as seen for those with lower CRP values) and a 1.8-fold higher risk for disease severity." (PMID 37388734, 2023). "Similarly, some other studies suggest that C Reactive Protein (CRP) level may predict the risk of COVID-19 aggravation." (PMID 36983064, 2023). "Another study, involving a series of 25 cancer patients with COVID-19 in northern Italy, found that female gender (p = 0.04), multiple primary tumor locations (e.g. genitourinary and hematologic) (p = 0.02), and elevated CRP (p = 0.047) were associated with higher mortality." (PMID 37363191, 2023). "Furthermore, COVID-19 and CRP were found to be independent factors associated with MDW, suggesting that MDW (cut-off value: 21.3) may be used as a screening test for COVID-19 in fever outpatients." (PMID 36973757, 2023). "Similarly, except for PCT (r = 0.112, p = 0.147) and LDH (r = 0.116, p = 0.130), the positive association of WBC (r = 0.281, p = 0.000), CRP (r = 0.442, p = 0.000) and ferritin (r = 0.181, p = 0.018) with COVID-19 severity remained significant after adjusting for age albeit week." (PMID 36678211, 2023). "Enhanced blood levels of IL-6, C-reactive protein (CRP), D-dimer, and ferritin are indicators of increased cytokine release and may be linked to systemic inflammation and hypoxemic respiratory failure caused by COVID-19." (PMID 37504277, 2023). "Our data are consistent with those obtained from a cohort of patients with COVID-19 who were aged and/or had high-risk comorbidities, in whom low levels of Plg were associated with worse prognostic parameters such as higher levels of IL-6, CRP, and markers of organ dysfunction." (PMID 36917195, 2023). "Considering the whole study population, SARS-CoV-2 pneumonia/COVID-19 status remained significantly associated with FVIIa-AT plasma levels by multiple linear regression models, even after adjustment for potential confounders, such as sex, age, CRP, eGFR, fibrinogen, PT, and aPTT." (PMID 36428852, 2022). "CRP blood level positively correlates with the percentage of lung involvement in COVID-19 patients on CT scans and could be used for predicting lung damage >25%; in multivariable analysis, CRP remains independently associated with COVID-19-related lung damage severity (OR 1.012 [1.003–1.022])." (PMID 36555850, 2022). "Similarly, CRP and D-dimer levels are associated with the disease progression and severity of COVID-19 and may predict mortality in hospitalized patients." (PMID 35997994, 2022). "Altered CRP levels may be linked to the degree of disease severity among COVID-19 patients." (PMID 35976368, 2022). "Further, we demonstrated the usefulness of DNAm surrogate biomarkers in investigating COVID-19 susceptibility and severity, showing that DNAmBMI was associated with case–control status, while measured BMI was not, and that DNAmCRP outperformed blood measured CRP in predicting disease severity." (PMID 36175966, 2022). "C-reactive protein (CRP) is one of the biomarkers related to coronavirus disease 2019 (COVID-19)." (PMID 35159761, 2022). "Also, NLR ≥ 3.3 (OR, 9.1; 95% CI, 1.9–42), CRP ≥ 30 mg/L (OR, 4.1; 95% CI, 1.2-13.6), D-dimer ≥ 1000 ng/mL (OR, 4; 95% CI, 1.5–10.7) and age (OR, 1.11; 95% CI, 1.04–1.18-year increase) were identified as risk factors for mortality among COVID-19 patients." (PMID 36404511, 2022). "Therefore, an elevated CRP level may be an important risk factor for predicting COVID-19 severity, even in patients with lung cancer." (PMID 36316726, 2022). "It is based on the pathophysiological hypothesis that CRP, in COVID-19, triggers a fulminant innate immunity autoimmune reaction in the human body which may be the real cause for the deleterious course in subjects with severe COVID-19 (Please see Section 3.5)." (PMID 35407379, 2022).